SIRT6 (sirtuin 6)
Diseases named in the same sentence as SIRT6 in open-access papers (continued):
Sharing a sentence is not in itself a finding about the gene and the disease.
Hypoglycemia (38 papers, 2011 to 2025). A decreased concentration of glucose in the blood. "Sirt6-deficient mice present with reduced body size, loss of subcutaneous fat, lordokyphosis, osteopenia, and lethal hypoglycemia at postnatal 2–3 weeks, highlighting the regulatory role played by Sirt6 in glucose metabolism." (PMID 40050262, 2025). "Sirt6 whole-body knockout (deletion of exon 1) mice on the 129S genetic background exhibit growth retardation and metabolic (hypoglycemia) and developmental defects (loss of subcutaneous fat, lordokyphosis, and lymphopenia) and die at about 4 weeks of age." (PMID 36831330, 2023). "The fundamental role of Sirt6 in regulating glucose metabolism was firstly identified by evidence which reports of serious hypoglycemia in Sirt6-deficient mice, in accordance with increased glucose uptake from muscle and adipose tissue." (PMID 37497437, 2023). "Sirt6 systemic knockout causes severe hypoglycemia and premature death, while transgenic mice overexpressing SIRT6 have an extended lifespan in males." (PMID 36057627, 2022). "Early studies showed that Sirt6-deficient mice presented with lethal hypoglycemia, highlighting the regulatory role played by SIRT6 in glucose metabolism." (PMID 36465178, 2022). "SIRT6 plays a potential role in regulating glucose since its deficiency leads to hypoglycemia by increasing insulin signaling and activating protein kinase, protein kinase B (Akt)." (PMID 33920726, 2021). "SIRT6 knockout mice die several weeks after experiencing hypoglycemia, osteopenia, and lymphopenia, while SIRT6-deficient monkeys only live several hours after birth, experiencing similar defects." (PMID 33067423, 2020). "Hypoglycemia was reported to be a direct cause of early death of SIRT6 KO mice, and the high‐fat diet can increase the blood glucose level by inhibiting glucose uptake." (PMID 31967391, 2020). "It has been reported that SIRT6 can regulate glucose homeostasis, and SIRT6 deficiency results in hypoglycemia and increases glucose uptake by overactivation of AKT." (PMID 31967391, 2020). "SIRT6 is also heavily implicated in metabolic regulation, and SIRT6−/− mice die at 2–4 weeks of age due to severe accelerated aging and hypoglycemia as a result of altered rates of glycolysis, glucose uptake, and mitochondrial respiration." (PMID 32331482, 2020). "The idea that SIRT6 inhibits glucose metabolism and inflammation is further supported by the observations that Sirt6 deficiency in mice causes early postweaning lethality from severe hypoglycemia." (PMID 30914513, 2019). "Sirt6-deficient mice die about 4 weeks of age, exhibiting severe metabolic defects, including low insulin and hypoglycemia." (PMID 30574122, 2018). "A hypoxia-inducible factor 1α (HIF-1α) inhibitor would rescue the hypoglycemia phenotype in SIRT6 deficiency mice." (PMID 30559718, 2018). "SIRT6-deficient mice have also shown signs of hypoglycemia, loss of subcutaneous fat, curved spines, and diminished levels of insulin growth factor-1 (IGF-1)." (PMID 29966233, 2018). "When the mice were fed water containing 10% glucose, blood glucose was increased and about 83% of the mice with whole-body Sirt6 deficiency survived, indicating the hypoglycemia was a main factor in the postnatal lethality." (PMID 29535637, 2018). "In SIRT6 deficiency mice, increased Akt phosphorylation and activated insulin signaling is observed, yielding more glucose uptake and even hypoglycemia." (PMID 30559718, 2018). "SIRT6-KO mice exhibit reduced body size and weight with severe hypoglycemia, lymphopenia, loss of bone mineral density (BMD), spinal curvature and loss of subcutaneous fat." (PMID 28928419, 2017). "SIRT6-KO mice suffer with severe hypoglycemia, which is associated with enhanced rate of glucose uptake by skeletal muscle." (PMID 28928419, 2017).
Hypoglycemia (continued). "We have previously demonstrated that SIRT6 regulates glucose homeostasis and that SIRT6 deficiency results in severe hypoglycemia by enhancing insulin-stimulated glucose uptake in mice, leading to death of the majority of mice within 10 days after weaning." (PMID 28355567, 2017). "Loss of Sirt6 in a 129Sv strain background caused severe hypoglycemia that resulted in death by 1 month post-partum." (PMID 25085992, 2014). "Subsequent studies have shown that this hypoglycemia results from elevated tissue uptake of blood glucose in SIRT6-deficient mice, despite their lower circulating insulin levels." (PMID 25085992, 2014). "Our previous studies demonstrated that SIRT6 deficiency in mice renders a phenotype characterized by a profound hypoglycemia due to increased glucose uptake." (PMID 24896097, 2014). "In fact, regulation of glucose flux by SIRT6 appears critical because SIRT6 deficiency causes a lethal hypoglycemia." (PMID 23408731, 2013). "For example, SIRT6 functions in genomic stability and transcriptional control of glucose metabolism and its deficiency (SIRT6-/-) causes a lethal hypoglycemia." (PMID 22115311, 2011). "SIRT6 knockout (SIRT6 KO) mice develop acute loss of subcutaneous fat, spontaneous colitis, hypoglycemia, osteopenia, and muscle atrophy at approximately 3 weeks of age, succumbing to death by 4 weeks; therefore, they are useful as a premature aging research model." (PMID 36567449, 2023). "SIRT6 deficiency increases insulin-stimulated glucose uptake by activating insulin signaling, which may be involved in severe hypoglycemia in global Sirt6 KO mice." (PMID 38201252, 2023). "Consequently, SIRT6 deficiency increases glucose uptake with upregulation of glycolytic enzymes, causing severe hypoglycemia in mice." (PMID 38201252, 2023). "It is therefore difficult to establish whether the observed muscle phenotype is a direct outcome of SIRT6 deficiency, or it is due to secondary effects resulting from systemic complications such as severe hypoglycemia." (PMID 36109503, 2022). "Indeed, SIRT6-knockout micedisplay increased glycolytic pathway associated with high glucoseuptake, increased insulin signaling, and severe hypoglycemia as acompensatory response." (PMID 34213345, 2021). "SIRT6 knockout mice develop severe hypoglycemia and other defects causing death." (PMID 33274005, 2020). "Hypoglycemia has been reported to be the direct cause of the early death of SIRT6 KO mice, and the high‐fat diet effectively increased the blood glucose level and triglyceride level in both male and female SIRT6 KO mice." (PMID 31967391, 2020). "Moreover, when mice with Sirt6 deficiency were treated with an Hif-1α inhibitor, the hypoglycemia phenotype was rescued, which suggests that increased activity of Hif-1α contributes to the impaired glucose metabolism in these mice." (PMID 29535637, 2018). "The first clue that Sirt6 might play a role in glucose metabolism came from a severe hypoglycemia phenotype observed in Sirt6-deficient mice." (PMID 29535637, 2018). "Mice with whole-body Sirt6 deficiency showed severe hypoglycemia." (PMID 29535637, 2018). "SIRT6-deficient mice, while born normally, develop acute degenerative processes including severe loss of subcutaneous fat, lymphopenia and osteopenia and die within the first month of life of acute onset hypoglycemia." (PMID 30216989, 2018). "SIRT6 deficiency also results in hypoglycemia and impairment of energy homeostasis, suggesting that SIRT6 could play an important role in regulating adipocyte differentiation." (PMID 28355567, 2017). "SIRT6 knockout mice appear normal at birth, but they rapidly develop a degenerative process that includes loss of subcutaneous fat, lymphopenia, osteopenia, and acute onset of hypoglycemia, leading to death in less than one month of age." (PMID 24896097, 2014).
Hypoglycemia (continued). "It has been described that SIRT6 deficiency in mice renders a phenotype characterized by a profound hypoglycemia and that SIRT6-dependent deacetylation of histone H3 at lysines 9 and 56 is required for the regulation of genes associated with glucose metabolism, including GLUT1." (PMID 24896097, 2014). "Notably, hypoglycemia is widely considered to be one of the main causes of death in SIRT6 KO mice." (PMID 36567449, 2023). "SIRT-6 interacts with insulin-dependent glucose transporter type 4 (GLUT-4) to prevent hypoglycemia." (PMID 39124846, 2024). "Sirt6 knockout mice exhibit fatal hypoglycemia due to increased glucose uptake, while SIRT6 overexpression enhances insulin sensitivity and glucose uptake 3,33." (PMID 38904020, 2024). "Sirt6 null mice that survive from hypoglycemia suffer progressive hepatic inflammation starting at 2 months of age." (PMID 36831330, 2023). "A seminal work in the study of SIRT6 described that global SIRT6 KO mice suffer a severe multisystemic phenotype, with severe hypoglycemia and a short life expectancy." (PMID 33572672, 2021). "In a previous study, it has been seen that mice with SIRT6 deficiency showed elevated uptake of glucose by tissue, high expression of glucose transporter glucose transporter 1 (GLUT1), and thus produced hypoglycemia." (PMID 33920726, 2021). "SIRT6-defiencicy mice showed fatal hypoglycemia, suggesting that SIRT6 is involved in glucose metabolism." (PMID 33109235, 2020). "The SIRT6 KO induced severe hypoglycemia resulting from excessive glucose uptake and anaerobic glycolysis, which also promoted overutilization of stored lipids and glycogen." (PMID 31967391, 2020). "And, the Sirt6 knockout mice showed severe hypoglycemia by enhancing insulin signaling and subsequent glucose uptake." (PMID 21373642, 2011). "The lifespan of Sirt6 ko mice was dramatically increased by HFD to 26 and 37 weeks in male and female mice, respectively, with a reversal of multi-organ atrophy, body weight loss, hypoglycemia, and premature aging." (PMID 38016059, 2023). "In our study, we found that at the same calorie intake, a high‐fat diet dramatically increased the lifespan of SIRT6 knockout mice to 26 weeks (males) and 37 weeks (females), reversed multi‐organ atrophy, and reduced body weight, hypoglycemia, and premature aging." (PMID 31967391, 2020). "SIRT6 deficiency increases GLUT1 expression on the cell surface (increasing glucose uptake,) as well as upregulates the expression of several of the key glycolytic enzymes causing hypoglycemia in mice." (PMID 30216989, 2018). "This posits the theory that the liver may be trying to compensate for the onset of hypoglycemia that results from this lower expression of SIRT6." (PMID 29966233, 2018). "Whole-body ablation of Sirt6 in mice results in severe hypoglycemia." (PMID 29535637, 2018). "Whole-body ablation of Sirt6 in mice resulted in severe hypoglycemia." (PMID 29535637, 2018). "Moreover, Sirt6 knockout (ko) mice are born normally but quickly exhibit characteristics of premature aging with profound lymphopenia, severe hypoglycemia, and greatly reduced serum levels of insulin-like growth factor 1 (IGF-1), ultimately leading to early death by around 4 weeks." (PMID 38016059, 2023). "The Sirt6−/− model may be of particular relevance to our study, because, similarly to Iqgap2−/− mice, its HCC gene signature included vast overexpression of Afp, and Sirt6−/− mice also displayed a distinct metabolic phenotype which included hypoglycemia and increase fat deposition." (PMID 23951254, 2013). "SIRT-6 interacts with insulin-dependent glucose transporter type 4 (GLUT-4), preventing hypoglycemia." (PMID 39124846, 2024). "In the absence of Sirt6, hepatic gluconeogenesis was significantly elevated, which suggests a compensatory response to hypoglycemia." (PMID 29535637, 2018). "For example, Sirt6 full knock-outs die due to hypoglycaemia, whereas neuron-specific deletion of Sirt6 does not have the same effect." (PMID 27763519, 2016).
Hypoglycemia (continued). "Additionally, neural-specific Sirt6-KO mice did not develop fatal hypoglycemia but presented with growth retardation and eventually became obese." (PMID 36465178, 2022). "Therefore, hypoglycemia in SIRT6 KO mice and growth retardation in NSIRT6 KO mice were not due to SIRT6 deficiency in POMC neurons." (PMID 33572672, 2021). "In the absence of SIRT6 function, mice develop lethal hypoglycemia." (PMID 25085992, 2014).
prostate carcinoma (34 papers, 2015 to 2026). A carcinoma that arises from epithelial cells of the prostate gland. "Loss of SIRT6 significantly suppressed proliferation and metastasis of prostate cancer cell lines both in vitro and in vivo." (PMID 33995674, 2021). "Taken together, these results indicated that higher levels of SIRT6 were associated with unfavorable progression in prostate cancer." (PMID 33995674, 2021). "Our data showed that the expressions of both SIRT3 and SIRT6 are dramatically increased, which is closely linked with the overall survival of prostate cancer patients." (PMID 33282964, 2020). "Herein, we investigated the role and underlying mechanisms of SIRT6 in prostate cancer progression." (PMID 33995674, 2021). "In patients with colon carcinoma, osteosarcoma or prostate cancer, Sirt6 expression level and overall survival are inversely related." (PMID 41530841, 2026). "For example, a study reported that Sirt6 can accelerate prostate cancer development by suppressing the innate immune response." (PMID 41530841, 2026). "By contrast, in prostate cancer, SIRT6 expression is elevated and correlates with advanced stage, higher Gleason scores, and reduced survival." (PMID 41463311, 2025). "To summarize, these findings indicate that SIRT6 plays a dualistic role in urinary system cancers, with tumor-suppressive effects in bladder and kidney cancers and tumor-promoting activity in prostate cancer." (PMID 41463311, 2025). "While the promise of SIRT6 inhibition marks an exciting frontier in cancer treatment, further research is essential to fully harness its therapeutic potential in prostate cancer." (PMID 39796040, 2024). "As demonstrated, an aptamer-modified exosomes carrying SIRT6-targeted siRNA significantly inhibited the growth and metastasis of prostate cancer both in vitro and in vivo through silencing SIRT6." (PMID 38802766, 2024). "Tissue microarray studies confirmed the higher levels of SIRT6 in both prostate tumor tissues and prostate cancer cells than in their normal counterparts." (PMID 38136586, 2023). "Knockdown of SIRT6 in human prostate cancer cells increased apoptosis by leading to sub-G1 phase arrest of the cell cycle and downregulating the expression of BCL2, as well as elevated DNA damage levels." (PMID 38136586, 2023). "On the other hand, the silencing of Sirtuin 6 (SIRT6) in prostate cancer cells via SIRT6-siRNA expressed in HEK 293 cell-derived EVs decreases tumor cell proliferation and metastasis via a NOTCH-related mechanism." (PMID 37175226, 2023). "Knockdown of SIRT6 in prostate cancer cells results in cell cycle arrest at sub-G1 phase, increased apoptosis, increased DNA damage, and decreased BCL2 expression, thereby reducing cancer cell viability and enhancing chemotherapeutic sensitivity." (PMID 35463332, 2022). "Another recent study also demonstrated that SIRT6 promotes the progression of prostate cancer by negatively regulating the Wnt/β-Catenin signaling pathway, as shown by a decrease in the expression levels of c-Myc, cyclin D1, and β-Catenin." (PMID 36291902, 2022). "The objective of our study was to explore the function and mechanism of SIRT6-induced regulation of prostate cancer (PCa)." (PMID 35251169, 2022). "In another work, Exos loaded with siRNA silenced SIRT6 in vitro and in vivo, resulting in SIRT6 deletion and a substantial reduction in prostate cancer cell growth and metastasis in mice." (PMID 36531952, 2022). "This indicates that SIRT6 promotes the survival and proliferation of prostate cancer by increasing Bcl-2 expression and preventing cell cycle arrest." (PMID 36291902, 2022). "Then we collected another 13 human biopsies of prostate cancer with different Gleason grade scores to assess SIRT6 protein levels." (PMID 33995674, 2021). "Further, we expanded the prostate cancer tissue number by performing IHC staining of SIRT6 in prostate cancer tissue microarray which was categorized by Stage score." (PMID 33995674, 2021).